RPH3AL (rabphilin 3A like (without C2 domains))
Description:
Rab GTPase effector involved in the late steps of regulated exocytosis, both in endocrine and exocrine cells (By similarity). Acts as a potential RAB3B effector protein in epithelial cells.
Synonyms: NOC2
Tractability: No criterion of Open Targets' tractability assessment is met for any kind of drug.
Gene: Protein-coding gene on chromosome 17 (212,389 to 386,376, reverse strand). Ensembl gene ENSG00000181031.
Subcellular location: Cytoplasm; Cytoplasmic vesicle, secretory vesicle membrane
Gene Ontology:
Molecular function: protein binding; cytoskeletal protein binding; small GTPase binding
Biological process: calcium-dependent activation of synaptic vesicle fusion; exocytosis; positive regulation of calcium ion-dependent exocytosis; glucose homeostasis; intracellular protein transport; positive regulation of insulin secretion
Cellular component: cytoplasm; synapse; presynapse; transport vesicle membrane
Genetic constraint (gnomAD): Loss-of-function variants: 38 observed, 41.19 expected, observed/expected ratio (o/e) 0.92, 90% interval 0.71 to 1.21. The upper end of that interval is the gene's LOEUF score, 1.21, which puts it in group 5 of 6, group 1 being the genes least tolerant of losing a copy. Missense variants: 462 observed, 406.03 expected, observed/expected ratio (o/e) 1.14, 90% interval 1.05 to 1.23. Synonymous variants: 189 observed, 167.98 expected, observed/expected ratio (o/e) 1.13, 90% interval 1 to 1.27.
Homologues: Orthologues: chimpanzee RPH3AL (88% identical), macaque RPH3AL (86% identical), guinea pig RPH3AL (80% identical), mouse Rph3al (78% identical), rat Rph3al (77% identical), pig RPH3AL (53% identical), dog RPH3AL (52% identical), tropical clawed frog rph3al (50% identical), Drosophila melanogaster Rph (34% identical). Paralogues in human: RPH3A (36% identical), SYTL5 (18% identical), SYTL3 (17% identical), SYTL4 (17% identical), SYTL1 (13% identical), SYTL2 (12% identical), DOC2B (12% identical), DOC2A (11% identical), SYT16 (11% identical), SYT9 (10% identical), SYT10 (10% identical), SYT14 (10% identical), and 19 more.
Diseases named in the same sentence as RPH3AL in open-access papers:
RPH3AL is named in the same sentence as 17 diseases in open-access papers, as found by Europe PMC text mining. Sharing a sentence is not in itself a finding about the gene and the disease. The quoted sentences say what the papers report.
bladder cancer (3 papers, 2012 to 2021). "We and others previously reported immunohistochemical expression of RPH3AL protein in normal and tumor tissues of human endocrine pancreas and bladder cancers." (PMID 26070152, 2015).
breast carcinoma (2 papers, 2015 to 2019). "Missense point mutations in the coding region of exon-6 of RPH3AL were present in 19 of 125 (15%) of breast cancers." (PMID 26070152, 2015). "Since our preliminary sequence analysis of RPH3AL showed mutations confined to exon-6, further sequencing of RPH3AL in 125 FFPE breast cancer specimens focused only on exon-6." (PMID 26070152, 2015). "Since LOH and SNPs at regulatory regions of genes influence their expression, as observed for thymidylate synthase (TS) and CYP17, we analyzed LOH of RPH3AL and evaluated the coding and non-coding regions of RPH3AL for mutations and SNPs in breast cancers." (PMID 26070152, 2015). "Thus, genetic alterations in RPH3AL are associated with aggressive behavior of breast cancers and with short survival of patients." (PMID 26070152, 2015). "Also, our findings suggest that there is a need to increase the sample size to establish an independent prognostic value of allelic loss of RPH3AL in breast cancer." (PMID 26070152, 2015). "21% (6 of 28) of breast cancer cases exhibited mutations in the RPH3AL gene." (PMID 26070152, 2015). "Consistently, in breast cancer tissues, there were lower levels of RPH3AL protein in malignant breast cells (LIN, DCIS, and invasive carcinoma) relative to nonmalignant cells." (PMID 26070152, 2015). "Relationship between clinicopathological features and LOH status at 17p13.3 of the RPH3AL gene in breast cancers." (PMID 26070152, 2015). "Consistent with previous results, the present study found lower expression of RPH3AL mRNA in breast cancers relative to matching normal tissues." (PMID 26070152, 2015). "In conclusion, the correlations found between genetic alterations of RPH3AL with aggressive features of cancer indicate that genetic abnormalities of the RPH3AL gene are involved in breast cancer progression." (PMID 26070152, 2015). "Consistent with the nature of a tumor suppressor, mRNA and protein expressions of RPH3AL were low in breast cancer tissues relative to their corresponding control/benign tissues." (PMID 26070152, 2015). "Gene expression analysis demonstrated that the mRNA levels of RPH3AL were down-regulated in breast cancers relative to their matching normal tissues." (PMID 26070152, 2015). "For the rabphillin-3A-like (RPH3AL) gene, a putative tumor suppressor, the clinical significance of genetic alterations in breast cancers was evaluated." (PMID 26070152, 2015). "Relationship between clinicopathological features and SNPs at 5’UTR-25 and intron-6-43 of RPH3AL in breast cancers." (PMID 26070152, 2015). "Genetic abnormalities of the RPH3AL gene and demographic and pathological features of breast cancers." (PMID 26070152, 2015). "Four CpG sites located nearest the genes CTNNA2, GRB10, RPH3AL, and TINCR showed individual associations with breast cancer risk in a multivariable model (P < 0.05) and were also associated with breast cancer risk in matched case-control pairs in EPIC-Italy." (PMID 31039828, 2019).
colorectal cancer (2 papers, 2012 to 2015). A primary or metastatic malignant neoplasm that affects the colon or rectum. "It is of interest to note that a recent study suggests that RPH3AL may have a role as a tumor suppressor gene in a minority of colorectal cancer cases." (PMID 22724020, 2012).
diabetes (2 papers, 2015 to 2023). "Regarding hypomethylated DMRs, they involved genes linked to metabolic control of diabetes such as FN3K, RPH3AL and HOX, HDAC4." (PMID 36870961, 2023). "Others have been associated with diabetes (ZBED3), asthma (EMID2), and cancer (FBXO3, HOOK2, MT2A, EIF3E, RPH3AL, PTRF, MT1M, STK32A)." (PMID 25748564, 2015).
pancreatic cancer (1 paper, 2011). "In turn, common regions of LOH also included two genes that have been involved in pancreatic cancer: the RPH3AL and SERPINF1 genes at chromosome 17p13." (PMID 21811587, 2011).
preeclampsia (1 paper, 2025). Preeclampsia is a hypertensive disorder of pregnancy that is characterized by new-onset hypertension with proteinuria presenting after 20 weeks of gestation, and depending on mild or severe forms may initially present with severe headache, visual disturbances, and hyperreflexia. "In a further example, we speculate that DMR29 (proximal to RPH3AL) may not be caused directly by exposure to preeclampsia in utero, but could just be correlated." (PMID 41286963, 2025).
schizophrenia (1 paper, 2017). A major psychotic disorder characterized by abnormalities in the perception or expression of reality. "Of note, a DMR spanning four probes within the RPH3AL gene (which encodes a protein that plays a direct regulatory role in calcium-ion-dependent exocytosis), was consistently hypomethylated in schizophrenia patients across all four brain regions." (PMID 28011714, 2017).
type II diabetes (1 paper, 2023). "In addition, the RPH3AL and HOX genes are known to suffer DNA methylation alterations during adipogenesis in cells from obese patients with and without type II diabetes." (PMID 36870961, 2023).
tumor (5 papers, 2011 to 2017). "Other genomic regions with homozygous deletions also contained genes (MAP2K4 and miR-744 in 17p12 [Y15] and RPH3AL in 17p13.3 [Y12], respectively) that function as tumor suppressors or potential tumor suppressors in other cancers." (PMID 29190909, 2017). "Our previous studies showed that RPH3AL mRNA expression was decreased in CRCs and suggested its tumor suppressor role in these cancers." (PMID 26070152, 2015). "In our previous study, a higher prevalence of the mutant genotype at the 5’UTR-25 of RPH3AL and its association with a poor prognosis of CRC in White patients was noted, suggesting that there is substantial inter-individual variation in susceptibility to genetic events and to tumor development." (PMID 26070152, 2015). "The only known gene in the precise region chr17:118,535–134,424 is RPH3AL, but there exists no conclusive evidence for a tumor suppressive role despite the fact that loss of 17p13.3 is strongly associated with poor recurrence-free and disease-specific survival." (PMID 21386901, 2011).
cancer (4 papers, 2015 to 2021). A tumor composed of atypical neoplastic, often pleomorphic cells that invade other tissues. "Low levels of RNA and protein expression of RPH3AL were present in cancers relative to normal tissues." (PMID 26070152, 2015).
RPH3AL also shares sentences with these, for which no sentence is quoted: asthma (1 paper); breast neoplasm (1); cat-eye syndrome (1); colorectal adenocarcinoma (1); esophageal cancer (1); invasive carcinoma (1); lobular intraepithelial neoplasia (1).